CALN1 (calneuron 1)
Description:
Negatively regulates Golgi-to-plasma membrane trafficking by interacting with PI4KB and inhibiting its activity. May play a role in the physiology of neurons and is potentially important in memory and learning.
Synonyms: CaBP8
Tractability: Antibody: UniProt places it where antibodies can reach, with high confidence; UniProt predicts a signal peptide or a membrane-spanning region; its Gene Ontology location is reachable by antibodies, with medium confidence.
Gene: Protein-coding gene on chromosome 7 (71,779,491 to 72,447,151, reverse strand). Ensembl gene ENSG00000183166.
Subcellular location: Golgi apparatus, trans-Golgi network membrane; Cytoplasm, perinuclear region; Cell membrane
Subcellular location (Human Protein Atlas): Vesicles; Plasma membrane
Gene Ontology:
Molecular function: protein binding; calcium ion binding
Cellular component: trans-Golgi network membrane; Golgi apparatus; perinuclear region of cytoplasm; plasma membrane; postsynaptic density
Genetic constraint (gnomAD): Loss-of-function variants: 16 observed, 27.06 expected, observed/expected ratio (o/e) 0.59, 90% interval 0.4 to 0.9. The upper end of that interval is the gene's LOEUF score, 0.9, which puts it in group 3 of 6, group 1 being the genes least tolerant of losing a copy. Missense variants: 290 observed, 353.52 expected, observed/expected ratio (o/e) 0.82, 90% interval 0.74 to 0.9. Synonymous variants: 155 observed, 133.49 expected, observed/expected ratio (o/e) 1.16, 90% interval 1.02 to 1.33.
Homologues: Orthologues: chimpanzee CALN1 (100% identical), macaque CALN1 (99% identical), guinea pig CALN1 (98% identical), rabbit CALN1 (97% identical), tropical clawed frog caln1 (85% identical), mouse Caln1 (84% identical), zebrafish caln1 (80% identical), dog CALN1 (74% identical), zebrafish caln2 (73% identical), Caenorhabditis elegans cal-1 (20% identical), Caenorhabditis elegans cal-3 (20% identical), Caenorhabditis elegans E02A10.3 (19% identical), and 9 more. Paralogues in human: CABP7 (53% identical), CABP4 (27% identical), CABP2 (25% identical), CABP5 (24% identical), CABP1 (22% identical), CALM1 (21% identical), CALM2 (21% identical), CALM3 (21% identical), CALML3 (20% identical), CETN2 (18% identical), CETN1 (18% identical), CALML5 (16% identical), and 8 more.
Diseases named in the same sentence as CALN1 in open-access papers:
CALN1 is named in the same sentence as 26 diseases in open-access papers, as found by Europe PMC text mining. Sharing a sentence is not in itself a finding about the gene and the disease. The quoted sentences say what the papers report.
schizophrenia (9 papers, 2018 to 2024). A major psychotic disorder characterized by abnormalities in the perception or expression of reality. "In addition, CAPN9 and CALN1 are thought to be associated with gastric cancer and schizophrenia (Schizophrenia Psychiatric Genome-Wide Association Study (GWAS) Consortium, 2011), respectively." (PMID 30693022, 2018). "While this gene is relatively under-studied, a recent study has hypothesized that a micro-RNA (MIR137, also associated with schizophrenia risk) targets the CALN1 gene." (PMID 29652918, 2018). "Interestingly, a meta-analysis of the genetic association studies came to the conclusion that calneuron-1 mRNA levels might be up-regulated in schizophrenia in the dorsolateral prefrontal cortex." (PMID 30787867, 2019). "Furthermore, Caln1 contained 3 separate DMRs; as it contains a risk allele for schizophrenia in some human populations, it could also play a role in some of the neuropsychiatric deficits observed in individuals with FASD." (PMID 30568673, 2018). "The CALN1 (calneuron 1) is a candidate gene for schizophrenia and intelligence, which was discovered in independent GWASs." (PMID 36482414, 2022). "Three relatively recent studies from different groups propose that the human CALN1 is a candidate schizophrenia gene but it is at present unclear how calneuron-1 function can be related to psychotic behavior." (PMID 30787867, 2019). "While previous GWAS have identified variants in CALN1 as associated with lipid levels and schizophrenia, no prior GWAS had found associations between CALN1 variants and FA levels." (PMID 29652918, 2018). "In summary, although it is at present unclear how exactly both proteins contribute to the pathophysiology of schizophrenia, the basic characterization of their unique cellular role of calneuron-1 might pave the way to understand how they are involved in schizophrenia." (PMID 30787867, 2019). "Moreover, in addition to the relationship between the PI4KB activator NCS‐1 and schizophrenia, genetic and functional linkages were also observed between the PI4KB inhibitor CALN‐1 and schizophrenia." (PMID 32530132, 2021). "However, it has been shown that alteration in methylation levels on the CALN1 and the AUTS2 gene occur in schizophrenia patients." (PMID 30787867, 2019).
osteosarcoma (6 papers, 2019 to 2024). A usually aggressive malignant bone-forming mesenchymal neoplasm, predominantly affecting adolescents and young adults. "CALN1 might influence the invasion and migration of osteosarcoma cell line, and it was also associated with the survival of osteosarcoma." (PMID 32874133, 2020). "These exosomes mediated the transfer of miR-675 from osteosarcoma cells to stromal cells, and miR-675 downregulated the expression of calneuron 1 (CALN1), resulting in the promotion of migration and invasion of tumor cells." (PMID 35592419, 2022). "Metastatic osteosarcoma cells secrete exosomes containing high levels of miR-675 that induces migration and invasion in recipient fibroblasts by down-regulating CALN1." (PMID 32957712, 2020).
gastric cancer (5 papers, 2016 to 2019). A primary or metastatic malignant neoplasm involving the stomach. "Furthermore, this miRNA has been implicated in carcinogenesis and metastasis in gastric cancer by targeting Calneuron 1 (CALN1), a migration-related gene." (PMID 31533332, 2019). "Recently, it has been demonstrated that miR-675 have several targets in different cancers, such as c-Cbl and Cbl-b in breast cancer, GPR55 in lung carcinoma, Rb in colorectal cancer, CALN1 in gastric cancer, Cadherin 11 in melasma." (PMID 27120794, 2016). "Besides, H19 can enhance carcinogenesis and metastasis in gastric cancer via miR-675 and calneuron 1(CALN1)." (PMID 27429196, 2016). "Many targets of miR-675 have been proposed in different tumors, such as Twist1 and RB in hepatocellular carcinoma and colorectal cancer, CALN1 and RUNX1 in gastric cancer, TGFBI in prostate cancer." (PMID 26198047, 2016).
bladder cancer (3 papers, 2022 to 2025). "We previously conducted a preliminary experiment focused on calnuelon 1 (CALN1), using the Ion AmpliseqTM Methylation Panel for Cancer Research, and found that CALN1 is associated with the clinicopathological features of bladder cancer (unpublished data)." (PMID 36352401, 2022). "Hypomethylation of CALN1 has been reported to be associated with bladder cancer in adults and hydroxymethylation of CALN1 may be a biomarker that is useful for cervical cancer diagnosis and prognosis." (PMID 41012410, 2025). "Therefore, we suggest that CALN1 methylation percentage may be an indicator of high-risk bladder cancer and could be considered a useful biomarker for accurately predicting intravesical recurrence of non-MIBC." (PMID 36352401, 2022). "In this study, we investigated the usefulness of determining CALN1 methylation status as a biomarker for bladder cancer." (PMID 36352401, 2022). "We analyzed the relationship between the CALN1 methylation percentage and clinicopathological data of patients with bladder cancer." (PMID 36352401, 2022). "We investigated the usefulness of the methylation status of CALN1 as a biomarker for bladder cancer using methylation-sensitive restriction enzyme (MSRE)-quantitative polymerase chain reaction (qPCR)." (PMID 36352401, 2022). "As for the TCGA-BLCA biomarkers, among the DNA-methylation features, CALN1 hypomethylation has been proposed as a urinary diagnostic marker that stratifies high-risk, nonmuscle-invasive bladder cancer patients and improves recurrence prediction models." (PMID 41470046, 2025). "Although various trials have been conducted regarding the diagnosis and treatment of bladder cancer, methylation analysis of CALN1 and its association with bladder cancer has not been probed before." (PMID 36352401, 2022). "Our findings suggest that CALN1 methylation percentage could be a useful molecular biomarker for bladder cancer." (PMID 36352401, 2022). "We hypothesized that the regulation of calcium signal transduction through methylation of CALN1 is involved in the development and progression of bladder cancer." (PMID 36352401, 2022).
adrenal adenomas (1 paper, 2021). "Calneuron 1 (CALN1), localized in the endoplasmatic reticulum, binds calcium ions and positively correlates with the increased CYP11B2 expression in APAs in comparison to non-functioning adrenal adenomas." (PMID 34771744, 2021).
adrenocortical carcinoma (1 paper, 2018). "CALN1 was shown to potentiate aldosterone production and silencing CALN1 led to a decrease in Ca2+ storage in the endoplasmic reticulum and abrogated angiotensin II-mediated aldosterone secretion in an adrenocortical carcinoma cell line." (PMID 29642543, 2018).
Alzheimer disease (1 paper, 2022). A progressive, neurodegenerative disease characterized by loss of function and death of nerve cells in several areas of the brain leading to loss of cognitive function such as memory and language. "Gene-based analyses implicated AGXT2 and CALN1 for VL, while analyses of protein-protein interactions implicated synaptic proteins previously associated with Alzheimer disease biology, SYT9 and NRXN1 for VSTM; ZFAND5, GRIK2, and ZC3H18 for VL; and PRLHR for paragraph recall." (PMID 35974141, 2022).
behavioural disorders (1 paper, 2015). "Finally, many genes associated with neurological development and behavioural disorders were pinpointed (CACNG2, CALN1, ACCN3, EFNB3, DLGAP1 and ATP1B2)." (PMID 26100250, 2015).
chronic obstructive pulmonary disease (1 paper, 2025). A chronic and progressive lung disorder characterized by the loss of elasticity of the bronchial tree and the air sacs, destruction of the air sacs wall, thickening of the bronchial wall, and mucous accumulation in the bronchial tree. "Finally, and of particular significance to this pilot study, CALN1 has been found to be associated with the average daily number of cigarettes smoked among cohorts with chronic obstructive pulmonary disease." (PMID 41012410, 2025).
Hip dysplasia (1 paper, 2026). The presence of developmental dysplasia of the hip. "We identified three genome-wide significant novel loci, COL11A2, CALN1 and TRPM7, associated with hip dysplasia without dislocation." (PMID 41912496, 2026).
Intellectual disability (1 paper, 2016). "The deleted genes (MIR3914-1, WBSCR17 and CALN1) are not known to relate to intellectual disability." (PMID 27734896, 2016).
leukemia (1 paper, 2021). A malignant (clonal) hematologic disorder, involving hematopoietic stem cells and characterized by the presence of primitive or atypical myeloid or lymphoid cells in the bone marrow and the blood. "CALN1 has previously known to be overexpressed in ETV6-RUNX1 leukemia but its exact function is still unknown, while TUSC3 is reported to be a tumor suppressor gene." (PMID 33708624, 2021).
meningioma (1 paper, 2017). A generally slow growing tumor attached to the dura mater. "NME1, NFE2, SFN, PTN, CALN1, GABRA5 and several components involved in neural differentiation and receptors associated with neural transmitter were also found to illicit an autoimmune response in the meningioma patients indicating that there could be some alterations in these components." (PMID 28938569, 2017).
sarcoma (1 paper, 2023). A usually aggressive malignant neoplasm of the soft tissue or bone. "OS-derived exosomes containing miR-675 can induce proliferation and invasion, increasing the migration of non-malignant fibroblast cells by decreasing the expression of calneuron 1 (CALN1), which results in sarcoma growth and metastasis." (PMID 36979391, 2023).
tumor (4 papers, 2020 to 2022). "We found that CALN1 hypomethylation was significantly associated with advanced tumor stage, more histologically higher-grade tumors, and an increased risk of intravesical recurrence." (PMID 36352401, 2022). "Hypomethylation of CALN1 was associated with advanced tumor stage (P = 0.0007) and histologically high grade (P = 0.018)." (PMID 36352401, 2022). "A low CALN1 methylation percentage remained an independent prognostic factor after adjusting for tumor size in the multivariate analysis." (PMID 36352401, 2022). "We found that low CALN1 methylation percentage is consistent with the occurrence of advanced tumor stages, high-grade tumors, and higher intravesical recurrence rates." (PMID 36352401, 2022). "Exosomes containing miR‐675 have been demonstrated to facilitate tumor cell migration and invasion by targeting CALN1 in metastatic osteosarcoma." (PMID 32673448, 2020).
CALN1 also shares sentences with these, for which no sentence is quoted: cancer (3 papers); colorectal cancer (2); breast carcinoma (1); cervical cancer (1); glioma (1); hepatocellular carcinoma (1); lung carcinoma (1); melasma (1); mental disorder (1); Obesity (1); prostate carcinoma (1).